BIRC5 (baculoviral IAP repeat containing 5)
Diseases named in the same sentence as BIRC5 in open-access papers (continued):
Sharing a sentence is not in itself a finding about the gene and the disease.
glioma (continued). "Collectively, these results demonstrate that BIRC5 is highly expressed in glioma cells, likely resulting in increased cell migration." (PMID 35309512, 2022). "In this study, we uncover that BIRC5 expression was upregulated in diverse human cancer and correlated with poor prognosis, especially in glioma." (PMID 35309512, 2022). "In this study, we found that the DNA methylation level of BIRC5 was down-regulated in glioma tissues than normal tissues." (PMID 35309512, 2022). "Crosstalk between m6A RNA modification and BIRC5 expression in low-grade glioma, therefore, requires further characterization in future studies." (PMID 35309512, 2022). "This further confirmed the difference in transcriptional levels of BIRC5 within different grades of gliomas, with an upregulation in the grade IV gliomas or GBM." (PMID 35886952, 2022). "IHC assay results also indicated that BIRC5 was highly expressed in glioma tissues than paracancerous tissues." (PMID 35309512, 2022). "We used a quantitative real-time polymerase chain reaction (qRT-PCR) and Western blot assay to detect BIRC5 expression in normal human astrocyte cells and glioma cell lines." (PMID 35309512, 2022). "We recognized an inverse correlation in the expression between miR-138 and BIRC5 in all types of glioma." (PMID 34356844, 2021). "When the expression levels of miR-138 and BIRC5 were compared in each type of glioma, it was inversely correlated in all types of glioma at significant level." (PMID 34356844, 2021). "As BIRC5 expression becomes more predominant in higher-grade gliomas, there appears to be an opposing negative linear association with survival in animal and human models." (PMID 40422257, 2025). "For the sake of exploring whether BIRC5 downregulation can promote glioma cell apoptosis, the interference fragments of BIRC5 were screened." (PMID 37340587, 2023). "In conclusion, scutellarin may play an anti‐glioma role by regulating BIRC5 and affecting apoptosis." (PMID 37340587, 2023). "Our experimental results indicated that scutellarin may to exert its anti‐glioma effect through BIRC5." (PMID 37340587, 2023). "In addition, scutellarin can significantly reduce BIRC5 expression in order to reverse glioma cell apoptosis inhibition and to exert its anti‐glioma effect." (PMID 37340587, 2023). "Knock-down of BIRC5 significantly inhibits the cell migration of gliomas cells in vitro." (PMID 35309512, 2022). "Altogether, our results suggest that BIRC5 might serve as a valuable prognostic factor and a promising novel immunotherapy target for glioma." (PMID 35309512, 2022). "BIRC5 was highly expressed in glioma cell lines, especially in U251 cells." (PMID 35309512, 2022). "Finally, qRT-PCR was used to validate the expression of BIRC5 in normal human astrocytes cells and glioma cell lines." (PMID 35309512, 2022). "In addition, we found that in glioma tissues from the TCGA database, SAA1 levels were associated with a range of anti-apoptotic genes (Bcl-xl, BFL1, MCL1, BIRC5, and Fas) and pro-apoptotic genes (Bim, Bid, CASP9 and Apaf1)." (PMID 33854635, 2021). "In addition, scutellarin could significantly reduce the expression of baculovirus inhibitor of apoptosis protein 5 (BIRC5), thereby reversing the inhibition of apoptosis in glioma cells and exerting its anti-glioma effect." (PMID 38436812, 2024). "In order to make sure whether scutellarin promotes the apoptosis and inhibits the proliferation of glioma cells by downregulating BIRC5, scutellarin was added to U251 and LN229 cells, RT‐qPCR was used to detect the expression of the BIRC5 gene in U251 and LN229 cells after 48 h." (PMID 37340587, 2023).
glioma (continued). "In addition, the clinical follow‐up data of glioma patients from TCGA database was analysed, and it was found that the 5‐year survival rate of patients with BIRC5 upregulation was significantly lower than that of patients with BIRC5 downregulation." (PMID 37340587, 2023). "Therefore, we speculated that the higher expression of BIRC5 in low grade glioma patients might due to more low grade glioma patients are IDH wild-type tumors, which expressed higher BIRC5 levels." (PMID 35309512, 2022). "Additionally, BIRC5 expression is also associated with histology subtypes, IDH1 mutation, 1p/19q chromosomal co-deletion, chemotherapy status, and MGMT promoter methylation status, well-established molecular characteristics of gliomas." (PMID 35309512, 2022). "Elevated levels of YAP/TAZ mRNA and protein are significantly identified in glioma tissues alongside their target genes, namely cysteine-rich angiogenic inducer 61 (CYR61), CTGF, and baculoviral IAP repeat-containing 5 (BIRC5)." (PMID 39936032, 2025). "Additionally, knockdown of the expression of BIRC5 (Spearman’s coefficients = 0.939, p < 0.001) and RRM2 (Spearman’s coefficients = 0.936, p < 0.001), two additional top 50 TK1-associated coexpressed positive genes, inhibits the migration, proliferation, and apoptosis of glioma cells." (PMID 36831773, 2023). "Here, we evaluated BIRC5 expression and clinical characteristics in people with LGG using the Chinese Glioma Genome Atlas, The Cancer Genome Atlas, Gene Expression Omnibus, Rembrandt, and Gravendeel databases." (PMID 35309512, 2022). "MAPK3 and CX3CL1 were strongly positive; NFE2L2, HSP90AB1, and SUPT20H were moderately positive; and FKBP1B, BIRC5, NPC1, IKBKE, BID, and PTEN were weakly positive in glioma tissue relative to their expression levels in normal tissue." (PMID 33194668, 2020). "For signaling pathways genes, the expression of CXCR4, BIRC5, CTNNB1, FZD4, and MET were significantly increased in high-grade gliomas." (PMID 32154177, 2020). "The expression of BIRC5 in glioma tissues was significantly higher than that in normal brain tissues." (PMID 37340587, 2023). "RT‐qPCR was performed to detect the expression of BIRC5 and COL3A1 in glioma tissues and cells." (PMID 37340587, 2023). "It was found that BIRC5 had an abnormally high expression in glioma tissues and cells, while no significant change was observed in the expression of COL3A1." (PMID 37340587, 2023). "We examined microarray data of GSE111260 again and found that BIRC5 was highly expressed in grade 4 glioma, along with RUNX1 (p < 0.0001), supporting the possibility that high BIRC5 expression may contribute to a higher grade of malignancy." (PMID 36085167, 2022).
pancreatic cancer (25 papers, 2008 to 2025). "FL118 targeting the BIRC5 promotor has been linked to transcriptional inhibition, and anti-tumour activity, in multiple cancer types, including cervical and pancreatic cancer and leukaemia." (PMID 37298623, 2023). "Using univariate Cox regression, a forest map was generated showing seven ARGs associated with pancreatic cancer prognosis: BAK1, ITGA3, BIRC5, WDR45, BAG3, APOL1, and RAB24." (PMID 35488119, 2022). "The F-box and leucine-rich repeat protein 7 (FBXL7) is a potential tumor-suppressing gene, one that is frequently hypermethylated in pancreatic cancer and where the encoded protein promotes the degradation of AURKA, BIRC5 and c-SRC." (PMID 35887149, 2022). "Pamrevlumab has also been found to downregulate pro-survival factors XIAP and BIRC6 in a model of pancreatic cancer and the related inhibitor of apoptosis BIRC5 was among the RT-elevated, pamrevlumab-diminished genes identified in the current model." (PMID 29347981, 2018). "YM155 administration in a model with BIRC5 deletion shrank the metastatic foci in SW1990-bearing mice, thus indicating that BIRC5 in CTCs is a key coordinator of the metastasis of pancreatic cancer." (PMID 34745998, 2021). "Treatment of Capan-2, a pancreatic cancer cell line with autocrine WNT and HH signaling, with BAY ACC002, suppressed the expression of the WNT/β-catenin target genes AXIN2, BIRC5, MAD2L1 and OCT4." (PMID 27750213, 2017). "Overexpression of miR-181c induced hyperactivation of the YAP/TAZ and enhanced expression of the Hippo signaling downstream genes CTGF, BIRC5 and BLC2L1, leading to pancreatic cancer cell survival and chemoresistance in vitro and in vivo." (PMID 26561204, 2015). "Overexpression of miR-181c in human pancreatic cancer cells led to excessive activation of YAP/TAZ, along with increased expression of hippo signaling downstream genes CTGF, BIRC5, and BLC2L1, which improved the in vitro and in vivo survival and resistance of pancreatic cancer cells to chemotherapy." (PMID 39430767, 2024). "In pancreatic cancer, leptin (LEP) increases CD133 expression, the number of cells in the S phase, and overall progression and proliferation through increased expression of Notch receptors, ligands, and target molecules (NOTCH1-4, DLL4, JAG1, BIRC5 [survivin], and HEY2)." (PMID 39980929, 2025). "We found that miR-181c overexpression in pancreatic cancer cells significantly increased, but silencing of miR-181c reduced TEAD-dependent luciferase activity, and expression levels of the Hippo downstream genes CTGF, BIRC5 and BCL2L1 in pancreatic cancer cells." (PMID 26561204, 2015).
gastric cancer (22 papers, 2007 to 2025). A primary or metastatic malignant neoplasm involving the stomach. "No notable genetic alterations distinguishing the two groups were observed for other gastric cancer‐associated genes, such as BIRC5, MET, and MMP2." (PMID 41407509, 2025). "External validation showed that high BIRC5 expression was significantly associated with worse OS for breast-, lung-, and gastric cancer." (PMID 35331169, 2022). "In gastric cancer, high expression of BIRC5 promotes gastric cancer metastasis and is associated with poor prognosis." (PMID 34917126, 2021). "Overexpression of BIRC5 has been linked with the development and progression of esophageal, liver, colon, and gastric cancers." (PMID 34484469, 2021). "Down-regulation of TRIM27 can inhibit cell proliferation by inhibiting the Hippo-BIRC5 pathway and inducing 5-FU sensitivity in gastric cancer." (PMID 40936722, 2025). "In gastric cancer cells, hnRNPA2B1 binds to the exon 4 of BIRC5 pre‐mRNA adjacent to 3′ UTR, regulating its alternative splicing." (PMID 37850412, 2023). "This binding results in an increase in the pro‐cancer BIRC5‐202 isoform and a decrease in the anti‐cancer BIRC5‐203 isoform, promoting gastric cancer progression and chemotherapy resistance." (PMID 37850412, 2023). "Previously, increased transcription levels of c-myc, cyclin D1, c-jun, Wisp1 and Birc5 in the development and progression of gastric cancer were reported." (PMID 34594214, 2021). "hnRNPA2B1 promotes gastric cancer development and chemotherapy resistance partially through increasing the expression of BIRC5-202 transcript, which provide new treating opportunity for chemo-resistant patients." (PMID 34044823, 2021). "Hnrnpa2b1 regulates the alternative splicing of BIRC5 and promotes the progression of gastric cancer." (PMID 35252219, 2021). "Also BIRC5 was found related with prognosis of ccRCC and gastric cancer." (PMID 35237298, 2021). "BIRC5, CLDN1, DDX58, IL18, NPC2, NUSAP1, and PHC3 were found to have higher expression in gastric cancer tissues compared to normal tissues, and their expression was also elevated in various other cancer types." (PMID 40393971, 2025). "Consequently, the expression of several β-catenin target genes decreases, including Axin2, Lgr5, Cd44, Birc5, and c-myc, indicating that CCAR1 functions in the same way in gastric cancer cells as it does in colon carcinoma cells." (PMID 28230774, 2017).
liver cancer (21 papers, 2017 to 2025). An epithelial or non-epithelial malignant neoplasm that arises from the liver. "BIRC5 play key role in cell division and proliferation of liver cancer cells, but this gene might be linked with cell division and proliferation in pituitary prolactinoma." (PMID 33709028, 2021). "Spatial transcriptome analysis shows that STC2 and BIRC5 are mainly enriched in liver cancer cells and their mRNA and protein expression levels were greater in higher malignant HCC cell lines than in the lower ones." (PMID 40458412, 2025). "This in silico analysis identified a significant relationship between BIRC5 levels and liver cancer precursors (cirrhosis and fibrosis) compared to HCC." (PMID 37744383, 2023). "BIRC5 has been confirmed to be related to the occurrence of a variety of tumors, and its role in the progression of liver cancer has also been confirmed by studies." (PMID 37316840, 2023). "A subsequent multivariate survival analysis identified five key prognostic ARGs (ATIC, BAX, BIRC5, CAPNS1, and FKBP1A) that were used to construct prognostic risk models, which provided an accurate prognosis for patients with malignant liver tumors." (PMID 35402224, 2022). "The expression of BIRC5 was detected in 3/10 cases (30%), while positive expression of BIRC5 was found in 7/10 cases (70%) of liver cancer tissues." (PMID 33195412, 2020). "Baculoviral IAP repeat-containing protein 5 (BIRC5) was upregulated in liver cancer." (PMID 37393234, 2023). "Therefore, the expression levels of AURKA, BIRC5, CCNB1, CDK1, CDKN3 and TYMS served as diagnostic markers for liver cancer patients." (PMID 37393234, 2023). "Genetically modified animal model of liver cancer revealed that Birc5 depletion upregulated the genes related to lymphocyte‐mediated immunity, natural killer cell‐mediated immunity, interferon‐gamma production, T‐cell activation, and T‐cell‐mediated cytotoxicity." (PMID 37326143, 2023). "Similarly, studies indicated that BIRC5 played a key role in promoting cell proliferation and enhancing the sensitivity of liver cancer to chemotherapy." (PMID 37393234, 2023). "For example, the high expression of BIRC5 can promote the proliferation and angiogenesis of liver cancer cells, reduce the sensitivity to chemotherapy and radiotherapy, and suppress the apoptosis of tumor cells, thereby affecting the survival outcome of HCC patients." (PMID 34746309, 2021). "Moreover, BIRC5 was also found to be highly expressed in liver cancer." (PMID 36032071, 2022). "Our previous study found that traditional Chinese medicine could improve the tumor microenvironment of patients to treat liver cancer and speculated that the immune checkpoints CTLA-4, LAG-3, and BIRC5 are the key targets for activating immune cells to treat liver cancer." (PMID 34744733, 2021). "The results from TCGA database indicated that overexpression of ATIC, BIRC5, BAX, CAPNS1, and FKBP1A was closely related to an inferior OS of patients with liver cancer." (PMID 35402224, 2022). "Next, we analyzed the expression levels of ACTG1, CSNK1D, PPP1CC, and BIRC5 in HCC tissue samples in normal liver (n = 160) and liver cancer (n = 369) samples from the GEPIA dataset." (PMID 33816607, 2021). "Six genes (BIRC5, CACYBP, NR0B1, RAET1E, SPINK5, SPP1) were up-regulated in the liver cancer tissues compared to the normal tissues in the TCGA HCC dataset, and S100A8 was downregulated." (PMID 33568167, 2021). "We found that BIRC5, CDK1, NUF2, ZWINT, and SPC24 were highly expressed in liver cancer tissues, whereas expression was weak in normal tissues." (PMID 29190974, 2017). "By analyzing the whole‐genome expression profile of mouse liver cancer with or without BIRC5 depletion (GSE64804), 343 DEGs were obtained." (PMID 37326143, 2023). "Then, a 3‐gene prognostic model, including BIRC5, C8G, and SPP1, was constructed and validated in different datasets, which could better predict the prognosis of liver cancer." (PMID 37326143, 2023).
liver cancer (continued). "As expected, FEN1 expression was significantly positively correlated with that of MCM2, RFC4, and BIRC5 in TCGA liver cancer tissues, suggesting that FEN1 may be as involved in the development of HCC as are MCM2, RFC4, and BIRC5." (PMID 31534853, 2019). "Our data shows that BIRC5, NUF2, and SPC24 may be promising liver cancer biomarkers that may not only predict disease occurrence but also potential personalized treatment options." (PMID 29190974, 2017). "Furthermore, we analyzed the microarray data of an animal liver cancer model with or without BIRC5 depletion." (PMID 37326143, 2023). "The expression of FEN1 in TCGA liver cancer tissues was positively correlated with that of MCM2 (r = 0.853, P = 0.000), BIRC5 (r = 0.809, P = 0.000), and RFC4 (r = 0.852, P = 0.000), suggesting that FEN1 may play as important a role in the progression of liver cancer as do MCM2, BIRC5, and RFC4." (PMID 31534853, 2019). "Therefore, we suggested that BIRC5, NUF2, and SPC24 may be promising biomarkers in human liver cancer that provide information not only for predicting disease occurrence but also for suggesting personalized treatment options." (PMID 29190974, 2017). "Differ from STC2 and BIRC5 which were mainly expressed in liver cancer cells, EPO and GLP1R did not exhibit specific expression in a certain cell type, which could potentially be attributed to the fact that EPO and GLP1R may not predominantly expressed in HCC cell lines." (PMID 40458412, 2025). "Significantly, various known YAP/TEAD1 targeted genes, such as BIRC5, AREG, CCND1, CTGF, and MYC, were not activated through SRGN-mediated YAP signaling in liver cancer cell lines." (PMID 40384866, 2025).
colorectal cancer (20 papers, 2007 to 2025). A primary or metastatic malignant neoplasm that affects the colon or rectum. "Gene effect scores for DDX21 and BIRC5, derived from CRISPR-Cas9 loss-of-function screens across 40 colorectal cancer (CRC) cell lines in the Achilles project, were −0.8 and −1.5, respectively." (PMID 40362385, 2025). "Similar previous studies on colorectal cancer found a substantial positive correlation between BIRC5 expression and colorectal cancer stages, with BIRC5 expression being higher in stages II/III." (PMID 36358602, 2022). "EOMES overexpression in colorectal cancers was found to be important in the reciprocal regulation of BIRC5 and pro-apoptotic Bcl-2 modifying factor." (PMID 34685742, 2021). "BIRC5-specific T lymphocytes which recognize colorectal cancer cells and BIRC5-specific class I HLA-restricted T lymphocytes were activated and released interleukin 2 in response to HLA/ BIRC5-peptide complexes expressed by tumor cells." (PMID 33431968, 2021). "Specifically, we found that a subgroup of seven genes – BIRC5, CYCS, FZD3, FZD8, MAPK9, SMAD3, and SOS1 – that belong to the KEGG colorectal cancer pathway showed significant association with risk of BCC." (PMID 27367190, 2016). "BIRC5 has been identified in tumorigenesis and progress of colorectal cancer (CRC)." (PMID 29190974, 2017). "Therefore, BIRC5, as a target, might be useful for the treatment of drugs in gastric and colorectal cancers." (PMID 31093306, 2019). "23/25 (92%) colorectal cancer tissues were found to overexpress DR4, 19/25 (76%) were found to overexpress DR5 and 18/25 (72%) were found to overexpress BIRC5/Survivin." (PMID 27827395, 2016). "The expression of BIRC5 is up-regulated by the YAP1 in esophageal and colorectal cancer." (PMID 36768755, 2023). "Interestingly, HSH2D expression did not correlate with other genes associated with colorectal cancer metastasis and tumorigenesis, namely CDC20 and BIRC5." (PMID 39405604, 2024).